NDRG1 (N-myc downstream regulated 1)
Diseases named in the same sentence as NDRG1 in open-access papers (continued):
Sharing a sentence is not in itself a finding about the gene and the disease.
cervical cancer (10 papers, 2013 to 2026). A primary or metastatic malignant neoplasm involving the cervix. "Conversely, upregulation of NDRG1 expression in thyroid cancer and cervical cancer is significantly associated with tumor invasion, metastasis, and poor prognosis." (PMID 40151835, 2025). "Apart from its potent anti-metastatic role, NDRG1 has also been reported to play a pro-oncogenic role in many malignancies, including hepatobiliary, breast, and cervical cancers, and was associated with poor prognosis." (PMID 38970106, 2024). "In contrast, NDRG1 was found to be highly expressed in liver and cervical cancer tissues and its expression was associated with vascular invasion, metastasis, and poor prognosis." (PMID 23874544, 2013). "The integration of m5C-seq, mRNA-seq, and functional validation identified NDRG1 as a downstream target gene of NSUN6 in cervical cancer." (PMID 41462962, 2025). "The critical role of NDRG1 in HR repair provides a new research direction for the radiosensitization of cervical cancer." (PMID 38970106, 2024). "In summary, we provided compelling in vitro and in vivo evidence demonstrating that m5C and NSUN6 can regulate the radiosensitivity of cervical cancer via the regulation of NDRG1." (PMID 38970106, 2024). "Consistently, our data indicated that silencing NDRG1 has a tumor-suppressive effect in cervical cancer by inhibiting cell proliferation and promoting apoptosis." (PMID 38970106, 2024). "In this study, we first revealed that the downregulation of NDRG1 increases DNA damage and radiosensitivity in cervical cancer cells." (PMID 38970106, 2024). "Elevated NDRG1 enhances DNA damage repair, which promotes the radioresistance of cervical cancer and leads to a worse clinical prognosis." (PMID 38970106, 2024). "Collectively, our data provided novel evidence that NSUN6/ALYREF-mediated m5C modification maintained the stability of NDRG1 mRNA in cervical cancer." (PMID 38970106, 2024). "To investigate the effects of NDRG1 in cervical cancer radiosensitivity, we used small interference RNA (siRNA) treatment to silence NDRG1 expression in SiHa and Me-180 cells for functional test." (PMID 38970106, 2024). "Cell proliferation assay showed that transient NDRG1 knockdown significantly reduced the proliferation of human cervical cancer cells." (PMID 38970106, 2024). "NDRG1 overexpression promoted homologous recombination-mediated DNA repair, which in turn led to radioresistance in cervical cancer." (PMID 38970106, 2024). "Previous studies have suggested a role for this protein in mediating chemo- and radioresistance in different tumors, but, to the best of our knowledge, this is the first report highlighting a role for NDRG1 as a radio-responsive protein in cervical cancer." (PMID 31242951, 2019). "For instance, NDRG1 expression in breast, liver, lung and cervical cancers was positively correlated to the disease relapse and was a poor prognostic indicator for the patient survival." (PMID 23874544, 2013). "Finally, we characterized the relationships between NSUN6/NDRG1 expression and clinical prognosis in cervical cancer by performing IHC in 205 advanced cervical cancer tissues." (PMID 38970106, 2024). "Taken together, overexpression of hypoxia-pathway-related genes, such as NDRG1, HK2, and PLOD2, is induced by the OSM-STAT3 axis, and higher expression levels of these genes are significantly associated with poor prognosis in cervical cancer patients." (PMID 36551576, 2022). "Thus, we speculated that NDRG1 may promote DNA repair in cervical cancer by recruiting and stabilizing HR-related proteins, though the mechanism still requires further verification." (PMID 38970106, 2024). "By joint analysis of the expression of NSUN6 and NDRG1, we found that cases with high expression of both NSUN6 and NDRG1 tended to exhibit a worse prognosis in cervical cancer." (PMID 38970106, 2024).
cervical cancer (continued). "To investigate a putative role of ANXA2, NDRG1 and STAT1 on radiation/drug-mediated killing of tumor cells, we set up in vitro experiments using radiosensitive (C-4I) or radioresistant (CaSki) cervical cancer cells." (PMID 31242951, 2019). "In particular, the NDRG1, HK2, PLOD2, EGLN3, and NPC1 genes showed a higher expression in tumors than in normal tissues, and cervical cancer patients overexpressing these genes had a poor prognosis compared with those who showed low expression levels of these genes." (PMID 36551576, 2022). "To explore whether NDRG1 is engaged in the DDR pathway and thereby regulates cervical cancer radiosensitivity, we examined the role of NDRG1 in homologous recombination (HR) and non-homologous end joining (NHEJ) by performing I-Secl-based HR and NHEJ reporter assays, respectively." (PMID 38970106, 2024). "Overall, our findings suggest that the hypoxia-related genes, including NDRG1, HK2, and PLOD2, can be controlled by inhibiting STAT3, and this strategy is a novel therapeutic option that may effectively reduce the progression of cervical cancer." (PMID 36551576, 2022). "However, over-expression of FOXD3 into cervix cancer HeLa cells did not affect the NDRG1 expression, although resulting in decreased in vitro growth and invasion capabilities." (PMID 24269992, 2013). "However, NDRG1 was not an independent predictor of OS and RFS in cervical cancer." (PMID 38970106, 2024).
osteosarcoma (10 papers, 2017 to 2025). A usually aggressive malignant bone-forming mesenchymal neoplasm, predominantly affecting adolescents and young adults. "For the adjacent Ndrg1 gene, a reported biomarker for human osteosarcoma, we observed about a 7.5-fold increase in copy number and a 3.2 increase in transcription." (PMID 39457378, 2024). "On the other hand, abrogation of NDRG1 expression can sensitize osteosarcoma cells to combination therapy with combretastatin A-4 and chloroquine via suppression of autophagosome-lysosome fusion followed by promotion of apoptosis." (PMID 34077484, 2021). "In Osteosarcoma (OS), NDRG1 was shown to play an integral role in lysosomal function." (PMID 36497221, 2022). "Among these, the immunohistochemistry staining experiment supports the result from MS data that the N-Myc downstream regulated 1 (NDRG1) is overexpressed in osteosarcoma tissue compared to adjacent non-tumor tissues." (PMID 36077137, 2022). "Thus, NDRG1 may play completely different roles in the differentiation of osteosarcoma and non-neoplastic osteoblasts." (PMID 35120575, 2022).
esophageal squamous cell carcinoma (9 papers, 2017 to 2025). Esophageal squamous cell carcinoma (ESCC) is a type of esophageal carcinoma (EC) that can affect any part of the esophagus, but is usually located in the upper or middle third. "NDRG1 overexpression in esophageal squamous cell carcinoma (ESCC) is also reported to be associated with short OS in these patients." (PMID 30413609, 2018). "Ethyl protocatechuate was reported to induce cell autophagy and apoptosis through the upregulation of BNIP3 and NDRG1 (N-myc downstream-regulated gene-1) in esophageal squamous cell carcinoma cells." (PMID 37057280, 2023). "Other studies have shown that TLE2 is downregulated by NDRG1 overexpression in esophageal squamous cell carcinoma, thereby promoting tumor occurrence and development by activating the Wnt signaling pathway." (PMID 33747079, 2021).
liver cancer (9 papers, 2013 to 2025). An epithelial or non-epithelial malignant neoplasm that arises from the liver. "The mutation rate of NDRG1 in liver cancer reached up to 14%, and DNA methylation levels of NDRG1 and NDRG2 promoters correlated significantly with clinical prognosis." (PMID 35795037, 2022). "However, systematic evaluation of the diagnostic and prognostic values of NDRG1 or NDRG2 expression in liver cancer is poorly investigated." (PMID 35795037, 2022). "Reports have shown that Ndrg1 is increased in liver cancer, kidney cancer and other solid cancers, but it is decreased in colon, nervous system and other tumors." (PMID 36408272, 2022). "Prognostic performance of NDRG1 on clinical prognosis in various liver cancer patient subgroups by Cox regression analysis." (PMID 35795037, 2022). "However, NDRG1 is significantly upregulated in low‐to‐moderate differentiated liver cancer cells compared to well‐differentiated cancer cells." (PMID 40151835, 2025). "RT-qPCR showed that TFDP1, NDRG1, and FXR1 were expressed at higher levels in different liver cancer cell lines compared to normal liver cells." (PMID 37517087, 2023). "The C-indexes and calibration plots of the nomogram suggest that NDRG1 and NDRG2 have an effective predictive performance for OS (C-index: 0.676), DSS (C-index: 0.741) and PFI (C-index: 0.630) of liver cancer patients." (PMID 35795037, 2022). "We used the GSE39791 dataset for validation and could see that the expression of TFDP1, NDRG1 and FXR1 in liver cancer tissues was significantly higher than that in normal tissues." (PMID 37517087, 2023). "Finally, IHC results showed that the expression of FXR1 and NDRG1 was significantly higher in liver cancer tissues than in normal tissues." (PMID 37517087, 2023).
esophageal cancer (8 papers, 2013 to 2024). A primary or metastatic malignant neoplasm involving the esophagus. "In clinical samples of esophageal cancer, elevated levels of NDRG1 were associated with the malignant advancement of the disease." (PMID 39199357, 2024). "This suggests that NDRG1 in esophageal cancer cells plays a pro-oncogenic role through modulating tumor development." (PMID 37249826, 2023). "Our findings are consistent with previous reports that NDRG1 plays a role in promoting tumorigenesis in liver, kidney, and esophageal cancers." (PMID 35795037, 2022). "In summary, our observations indicated that AKR1C1/C2 promoted the inhibition of cell proliferation through either EDHB metabolism or BNIP3 and NDRG1 expression and induced early autophagy and late apoptosis in esophageal cancer cells." (PMID 26934124, 2016). "Previous research has also shown that EDHB inhibits esophageal cancer cell proliferation by increasing autophagy and apoptosis through NDRG1 and BNIP3 and markedly increases AKR1C1, AKR1C2, and AKR1C3 mRNA expression." (PMID 26934124, 2016). "AKR1C1/C2 facilitated the induction of early autophagy and late apoptosis by BNIP3 and NDRG1 in ESCC cells after EDHB treatment, thereby promoting the EDHB-induced inhibition of esophageal cancer cell proliferation." (PMID 26934124, 2016). "Furthermore, by modulating TLE2 and β-catenin expression, NDRG1 regulates Wnt pathway activation and EMT in esophageal cancer cells." (PMID 37249826, 2023). "Similar results were also observed in pancreas, prostate, breast and esophageal carcinoma tissue where the NDRG1 mRNA and protein levels were both decreased compared to normal counterparts." (PMID 23874544, 2013).
lymph node metastasis (7 papers, 2013 to 2025). "Lymph node metastasis (p = 0.034) and TNM stage (p = 0.025) were associated with high NDRG1 expression." (PMID 30914736, 2019). "The low expression of the proteins LTA4H, PGK1, NDRG1, COL6A1, and ITGAV in the saliva samples was associated with lymph node metastasis and advanced clinical staging (crosstabulation and chi-square test, P value < 0.05)." (PMID 30185791, 2018). "Moreover, multivariate Cox regression analysis identified tumor stage, lymph node metastasis, and NDRG1 expression as independent prognostic factors." (PMID 40539245, 2025). "Interestingly, SRM-MS analysis showed CSTB, LTA4H, PGK1, COL6A1, ITGAV, and NDRG1 were significantly downregulated in patients with lymph node metastasis." (PMID 30185791, 2018). "Specifically, lymph node metastasis (HR = 1.897, 95% CI: 1.113–3.234, p = 0.019), advanced tumor stage (III/IV) (HR = 2.203, 95% CI: 1.050–4.619, p = 0.037), and high NDRG1 expression (HR = 1.885, 95% CI: 1.209–2.937, p = 0.005) were all significantly associated with unfavorable clinical outcomes." (PMID 40539245, 2025). "NDRG1 expression was correlated with worse histological grade (P = 0.041) but not with lymph node metastasis (P = 0.655)." (PMID 31443698, 2019).
nasopharyngeal carcinoma (7 papers, 2021 to 2025). A carcinoma arising from the nasopharyngeal epithelium. "In addition, NDRG1 also upregulated E-cadherin expression by inhibiting the Smad2 pathway in nasopharyngeal cancer cells." (PMID 36293154, 2022). "By promoting the expression of NDRG1 (N-myc downstream regulated 1), CAPE inhibits the invasion and EMT of oral squamous cancer (SAS and OECM-1 cell lines) and nasopharyngeal carcinoma (TW01 and TW04 cell lines)." (PMID 40003984, 2025). "Our previous studies indicated that CAPE induced NDRG1 gene expression through the ERK signaling pathway to suppress the growth of oral (OSCC) and nasopharyngeal carcinoma (NPC) cells." (PMID 34662721, 2022). "A recent study reported that CYLD was downregulated in nasopharyngeal carcinoma and that CYLD overexpression promoted apoptosis by upregulating N-myc downstream regulated 1 (NDRG1)." (PMID 33919439, 2021). "Another example is a JUN-mediated seRNA, associated with metastasis (seRNA-NPCM), which forms an R-loop to simultaneously regulate distal target (NDRG1) and neighbouring (TRIB1) genes to promote the metastasis of nasopharyngeal carcinoma (NPC)." (PMID 38542080, 2024).
rectal cancer (7 papers, 2017 to 2023). A primary or metastatic malignant neoplasm that affects the rectum. "A protumorigenic role for NDRG1 is also supported in lung and rectal cancer, where increased NDRG1 is linked to reduced response to cisplatin and radiation therapy, respectively." (PMID 36765657, 2023). "Short hairpin RNA-mediated silencing of NDRG1 sensitized rectal cancer cell lines to clinically relevant doses of radiation by causing more DNA double strand breakages to rectal cancer cells when exposed to radiation." (PMID 29801473, 2018). "Taken together, we suggest that the higher NDRG1 expression may be associated with the radio-resistance of human rectal cancer cells, and it can be a potential therapeutic target for re-sensitizing radio-resistant rectal cancer cells to ionizing radiation." (PMID 29801473, 2018). "Analyzing radio-resistant human rectal cancer cells revealed an elevated expression of NDRG1 at both the mRNA and protein level." (PMID 36497221, 2022). "NDRG1 expression was shown to be significantly increased in radio-resistant rectal cancer (RC) cell lines and its silencing was shown to sensitize RC cells to relevant clinical doses of radiation by increasing DNA double strand breaks." (PMID 36497221, 2022). "Targeting NDRG1 represents a promising strategy to increase response to radiotherapy in human rectal cancer." (PMID 29801473, 2018). "This study aimed to investigate the effect of the reduced intracellular NDRG1 expression on radio-sensitivity of human rectal cancer cells for exploring novel approaches for treatment of rectal cancer." (PMID 29801473, 2018). "Among them, ERRFI1 and NDRG1 became final gene of interest as their mRNA and protein expression level was highly increased in radio-resistant rectal cancer cells." (PMID 29801473, 2018). "As far as we are concerned, our study is the first demonstration that rectal cancer can be stratified by NDRG1 status in terms of the response to chemotherapy." (PMID 28537875, 2017). "In addition, NDRG1 downregulation sensitizes radiotherapy-resistant human rectal cancer cells to radiation by increasing DNA double-strand breaks." (PMID 34077484, 2021). "Previous studies of rectal cancer cells have shown that NDRG1 is one of the top highly upregulated genes in response to ionizing radiation and that depleting it could be a promising strategy to sensitize cells to radiotherapy." (PMID 33321961, 2020). "This may imply that down-regulation of NDRG1 re-sensitized SNU-503R80Gy cells by disrupting rapid DNA damage recovery mechanism of radio-resistant rectal cancer cells." (PMID 29801473, 2018). "Inhibition of NDRG1 in these radio-resistant cells resulted in an increase sensitization of the cell to ionizing radiation while overexpression of NDRG1 re-instilled resistance in the cells, indicating a direct role of NDRG1 in radio-resistance in rectal cancer cells." (PMID 36497221, 2022). "A microarray analysis indicated the RNA expression of five genes (NDRG1, ERRFI1, H19, MPZL3, and UCA1) was highly increased in radio-resistant rectal cancer cell lines." (PMID 29801473, 2018). "The role of NDRG1 in resistance to ionizing radiation in rectal cancer has not been fully elucidated." (PMID 29801473, 2018). "Moreover, the relationship between the protein expression of NDRG1 and resistance to ionizing radiation in rectal cancer cell lines has not been studied." (PMID 29801473, 2018).
renal carcinoma (7 papers, 2013 to 2023). A carcinoma arising from the epithelium of the renal parenchyma or the renal pelvis. "The von Hippel-Lindau tumor suppressor E3 ubiquitin protein ligase has also been shown to down-regulate NDRG1 expression in renal cancer cells by targeting hypoxia inducible factor 1 for degradation." (PMID 24269992, 2013). "We propose that new therapies that selectively target the kinase that phosphorylates NDRG1 (Thr346) in renal cancer cells might be efficacious in ccRCC." (PMID 37298315, 2023). "Furthermore, the NDRG1 gene encoding N-myc downstream-regulated 1 protein (also called Cap43) can be upregulated in renal cancer cells, in which VHL protein is absent, potentially via induction of HIFs." (PMID 26703734, 2015). "Among the most altered genes, it has been shown that renal cancer progression can be promoted by upregulation of CXCL8, ADAM9, NDRG1, SOD2, SREBF1 and SREBF2 genes." (PMID 35505422, 2022).
Charcot-Marie-Tooth disease type 4D (6 papers, 2010 to 2025). "Mutations in NDRG1 (N-myc downstream-regulated gene 1) have been shown to be causative in the rare congenital subtype of Charcot-Marie Tooth Disease Type 4D, an inherited peripheral sensorimotor nerve disorder." (PMID 31138120, 2019). "Autosomal recessive NDRG1 null mutations result in Charcot-Marie-Tooth disease type 4D (CMT4D), a severe demyelinating peripheral neuropathy disorder." (PMID 29898756, 2018). "In addition, mutations in NDRG1 are known to cause a peripheral neuropathy related to demyelination, namely Charcot-Marie-Tooth disease type 4D (CMT4D), which we will further discuss in detail in the next section." (PMID 31485792, 2019). "The significance of this work is underscored by the well-documented role of N-cad in early development and cancer metastasis and may deeper inform our understanding of Charcot-Marie-Tooth disease type 4D, a neuropathy which has been linked to mutations in NDRG1." (PMID 40462946, 2025). "Furthermore, these findings may shed greater light on the etiology of Charcot-Marie-Tooth Disease type 4D, which has been linked to mutations in NDRG1." (PMID 40462946, 2025). "Charcot-Marie-Tooth Disease Type 4D (CMT4D), which has been linked to mutations in NDRG1, is characterized by demyelination of motor and sensory nerves leading to muscle weakness, atrophy, and sensory loss, typically beginning in the distal limbs." (PMID 40462946, 2025).
metastatic disease (6 papers, 2010 to 2025). "A study in the tissue section showed that a lower level of NDRG1 was related to metastatic tumors; however, the expression level of NDRG1 was correlated with invasion markers MMPs." (PMID 35563887, 2022). "In metastatic tumors, pathway and TF analyses revealed strong hypoxia-inducible factor-1α–driven hypoxia activation, influencing glycolysis (SLC2A1, SLC2A3, PGK1, PDK1, PGM1, and ALDOA), angiogenesis (ANGPTL4 and ADM), and survival in low oxygen (BNIP3, BNIP3L, and NDRG1)." (PMID 40736012, 2025).